MARVELD3 (MARVEL domain containing 3)
Description:
As a component of tight junctions, plays a role in paracellular ion conductivity.
Synonyms: MRVLDC3; MARVD3
Tractability: Antibody: UniProt predicts a signal peptide or a membrane-spanning region. PROTAC: ubiquitination databases record sites on it.
Gene: Protein-coding gene on chromosome 16 (71,626,161 to 71,642,114, forward strand). Ensembl gene ENSG00000140832.
Subcellular location: Membrane; Cell junction, tight junction
Subcellular location (Human Protein Atlas): Vesicles; Intermediate filaments
Gene Ontology:
Molecular function: mitogen-activated protein kinase kinase kinase binding; protein binding
Biological process: bicellular tight junction assembly; cell-cell junction organization; negative regulation of epithelial cell migration; negative regulation of epithelial cell proliferation; negative regulation of JNK cascade; protein localization to cell junction; response to osmotic stress
Cellular component: bicellular tight junction; cytoplasmic vesicle; membrane
Genetic constraint (gnomAD): Loss-of-function variants: 30 observed, 31.44 expected, observed/expected ratio (o/e) 0.95, 90% interval 0.71 to 1.29. The upper end of that interval is the gene's LOEUF score, 1.29, which puts it in group 5 of 6, group 1 being the genes least tolerant of losing a copy. Missense variants: 582 observed, 518.85 expected, observed/expected ratio (o/e) 1.12, 90% interval 1.05 to 1.2. Synonymous variants: 241 observed, 214.93 expected, observed/expected ratio (o/e) 1.12, 90% interval 1.01 to 1.25.
Homologues: Orthologues: pig MARVELD3 (71% identical), mouse Marveld3 (65% identical), chimpanzee MARVELD3 (57% identical), macaque MARVELD3 (53% identical), dog MARVELD3 (39% identical), rat Marveld3 (39% identical), zebrafish marveld3 (30% identical), tropical clawed frog marveld3 (28% identical). Paralogues in human: CACTIN (18% identical), PQBP1 (9% identical).
Diseases named in the same sentence as MARVELD3 in open-access papers:
MARVELD3 is named in the same sentence as 17 diseases in open-access papers, as found by Europe PMC text mining. Sharing a sentence is not in itself a finding about the gene and the disease. The quoted sentences say what the papers report.
pancreatic cancer (6 papers, 2016 to 2023). "MarvelD3 was transcriptionally downregulated during mesenchymal transition in pancreatic cancer cells, whereas its expression inhibits EMT, along with NF-κB pathway inactivation, a main regulator of EMT and cell metastasis." (PMID 36672179, 2023). "MarvelD3 has been reported to play a significant inhibitor role in colon adenocarcinoma cells and pancreatic cancer cells." (PMID 34338154, 2021). "MarvelD3 functions as a regulator of epithelial cell proliferation, migration, and survival in human colon and pancreatic cancer cells." (PMID 34338154, 2021). "Downregulation of marvelD3 is involved in EMT of human pancreatic cancer cells." (PMID 34338154, 2021). "MARVELD3 is downregulated in SNAIL-induced EMT during pancreatic cancer progression." (PMID 32260415, 2020). "In tumor cells, MarvelD3 was downregulated during EMT in human pancreatic cancer cells." (PMID 31783547, 2019). "Claudin-1 and −7, tricellulin and marvelD3 are involved in EMT in pancreatic cancer cells." (PMID 27121055, 2016). "Similar effects were also observed when MCF-7 breast cancer cells that are known to express MarvelD3 were compared to MiaPaca-2 pancreatic tumor cells, which do not express detectable MarvelD3." (PMID 31783547, 2019).
malaria (5 papers, 2014 to 2022). Malaria is a serious and sometimes fatal disease caused by a parasite that commonly infects a certain type of mosquito which feeds on humans. "The strong performance of our method in the context of a very well established predictor of malaria resistance, Hemoglobin S, serves as a positive control (method validation), and this further suggests that the conclusions about ATP2B4 and MARVELD3 should be useful." (PMID 25071867, 2014).
colorectal cancer (1 paper, 2020). A primary or metastatic malignant neoplasm that affects the colon or rectum. "Downregulation of MARVELD3 in colorectal cancer cells increases migration and proliferation, whereas upregulation inhibits migration, proliferation, and in vivo tumor formation." (PMID 32260415, 2020).
hepatocellular carcinoma (1 paper, 2021). A malignant tumor that arises from hepatocytes. "MarvelD3, a recently identified tight junction membrane protein, could be associated with hepatocellular carcinoma (HCC)." (PMID 34338154, 2021).
lung carcinoma (1 paper, 2020). "Similarly, MARVELD3 silencing decreases CDH1 and increases SNAI2 expression in lung cancer." (PMID 32260415, 2020).
ovarian carcinoma (1 paper, 2020). A malignant neoplasm originating from the surface ovarian epithelium. "Overall, these observations suggest that ILK regulates the JNK/c-JUN pathway in cisplatin-resistant ovarian cancer via modulation of DUSP8, MARVELD3, PDCD4, MAPK8IP1, MAPK8IP2, and HIPK3." (PMID 32260415, 2020).
pancreatic ductal adenocarcinoma (1 paper, 2021). An infiltrating adenocarcinoma that arises from the epithelial cells of the pancreas. "Since MarvelD3 is highly expressed in the pancreas, it would be interesting to assess its role in mice subjected to pancreatitis and/or pancreatic ductal adenocarcinoma (PDAC)." (PMID 34267243, 2021).
prostate tumors (1 paper, 2021). "Several other studies have shown that marvelD3 expression is more strongly reduced in cell lines with invasive phenotypes derived from breast, pancreatic, and prostate tumors than relatively normal cell lines." (PMID 34338154, 2021).
tumor (4 papers, 2019 to 2022). "In this study, we found that tumor tissue had lower expression level of marvelD3 than normal tissue and expression of marvelD3 was associated with TNM stage of HCC." (PMID 34338154, 2021). "When they were injected in a xenograft model, MarvelD3 overexpressing MiaPaca-2 cells revealed reduced tumor volume as compared to cells with low MarvelD3 expression." (PMID 31783547, 2019). "These evidences further validated the research value of MARVELD3 high expression in tumor tissues." (PMID 36353110, 2022). "In this study, we found that marvelD3 was downregulated in HCC tissues and its downregulation was obviously correlated with the tumor stage." (PMID 34338154, 2021). "However, marvelD3 knockdown did not affect tumor cell proliferation in vitro." (PMID 34338154, 2021).
cancer (3 papers, 2011 to 2021). A tumor composed of atypical neoplastic, often pleomorphic cells that invade other tissues. "However, in the MARVEL family, occludin, tricellulin, and marvelD3, little is known about changes in their expression during cancer progression." (PMID 34338154, 2021). "Previous studies have demonstrated that the correlation between marvelD3 and other cancers." (PMID 34338154, 2021).
MARVELD3 also shares sentences with these, for which no sentence is quoted: colitis (2 papers); breast carcinoma (1); colon adenocarcinoma (1); mesothelioma (1); oral squamous cell carcinoma (1); pancreatitis (1); ulcerative colitis (1).